Y_RNA (Y RNA )
Gene: Miscellaneous RNA gene on chromosome 11 (33,196,547 to 33,196,637, reverse strand). Ensembl gene ENSG00000200485.
Homologues: Orthologues: chimpanzee Y_RNA (100% identical). Paralogues in human: Y_RNA (93% identical), Y_RNA (92% identical), RNY3 (91% identical), RNY3P1 (91% identical), Y_RNA (91% identical), Y_RNA (90% identical), RNY3P14 (89% identical), Y_RNA (89% identical), Y_RNA (88% identical), RNY3P16 (87% identical), Y_RNA (87% identical), RNY3P11 (86% identical), and 93 more.